TRPV1 (transient receptor potential cation channel subfamily V member 1)
Diseases named in the same sentence as TRPV1 in open-access papers (continued):
Sharing a sentence is not in itself a finding about the gene and the disease.
glaucoma (13 papers, 2012 to 2025). Increased pressure in the eyeball due to obstruction of the outflow of aqueous humor. "In response to hydrostatic pressure, the cation channel transient receptor potential vanilloid 1 (TRPV1) is essential in signaling pathways linked to glaucoma." (PMID 35806371, 2022). "TRPV1 has also been implicated in neurodegenerative disorders such as Alzheimer’s disease, Parkinson’s disease, Huntington’s disease, and glaucomatous optic neuropathy, or glaucoma." (PMID 32273850, 2020). "This study supports that the endocannabinoid system may be involved in the loss of RGCs and that cannabinergic agents (CB1 or TRPV1 agonists and inhibitors of endocannabinoid metabolic enzymes) may be important therapeutics in glaucoma." (PMID 26881135, 2016). "RGC injury in Trpv1−/− mice and capsazepine-treated rats was associated with inhibited anterograde axonal transport of a fluorescently tagged marker, axonal loss and astrogliosis in the microbead occlusion glaucoma model." (PMID 25222270, 2014). "For example, intravitreal injection of methanandamide was found to rescue RGCs from retinal ischemia-reperfusion injury via activation of CB1 receptors and TRPV1 channels in an in vivo IOP-reperfusion model of glaucoma." (PMID 39861178, 2025). "Animal models simulating RGC degeneration, such as those for glaucoma, hold the potential to elucidate the role of TRPV1 and eventually offer insights for the development of neuroprotective strategies targeting TRPV1." (PMID 38256192, 2024). "In glaucoma models induced by elevated intraocular pressures, TRPV1′s expression in the RGCs increases." (PMID 38256192, 2024). "In models of glaucoma, genetic deletion of TRPV1 (Trpv1–/–) accelerates RGC axonopathy in the optic projection, whereas TRPV1 activation modulates RGC membrane polarization." (PMID 32273850, 2020). "The Ca2+-dependent apoptotic death of retinal ganglia cells, a neuronal subtype, subjected to experimental glaucoma in vitro was also found to require TRPV1, as did apoptosis of cortical neurons exposed to oxygen/glucose deprivation." (PMID 30838324, 2019). "Taken together, whether activation of TRPV1 is protective or toxic to RGCs might depend greatly on the expression levels because of this channel’s high Ca2+ conductance, the role of TRPV1 in glaucoma needs more studies to be better understood." (PMID 35185615, 2022). "Therefore, an increasing number of people pay attention to the functional properties of TRPV1 in the optic nerve during the progression of glaucoma." (PMID 35185615, 2022). "Cannabinergic agents, CB1 or TRPV1 agonists and inhibitors of endocannabinoid metabolic enzymes, may prove to be efficacious therapeutics in the treatment of glaucoma and diabetic retinopathy." (PMID 26881135, 2016). "In glaucoma, many insults such as excitotoxicity, ischemia, and activation of the transient receptor potential cation channel, subfamily V, member 1 (TRPV1) can lead to an increase in intracellular calcium concentration and therefore activate calcineurin." (PMID 23233785, 2012). "Interestingly, the enzyme calcineurin that is downstream of TRPV1 activation has been linked to RGC degeneration and death in animal models of glaucoma and calcineurin inhibition has been suggested as a neuroprotective strategy for glaucoma." (PMID 36231760, 2022). "Thus, in glaucoma and other age-related neurodegenerative diseases, TRPV1 may reconfigure NaV expression in neurons under stress to normalize excitability to existing metabolic resources." (PMID 32273850, 2020). "Indeed, TRPV1 activation that is not harmful in healthy tissue can be pathological during mechanical hyperalgesia and facilitated by pro-inflammatory molecules that have been implicated in glaucoma such as ATP, prostaglandins, and arachidonic acid metabolites." (PMID 30386208, 2018). "Moreover, loss of TRPV1 channels is not protective in mouse glaucoma models." (PMID 25222270, 2014).
glaucoma (continued). "As these events are particularly hazardous to RGCs, both pathological and neuroprotective aspects of TRPV1 and eCB activity may offer potential benefits for treating traumatic, inflammatory and ischemic optic neuropathies in diabetic retinopathy, ischemia, optic neuritis and glaucoma." (PMID 25222270, 2014).
oral cancer (13 papers, 2015 to 2025). "Trpv4 was more highly expressed than transient receptor potential cation channel subfamily A member 1 (Trpa1) and transient receptor potential cation channel subfamily V member 1 (Trpv1), channels associated with oral cancer pain in neurons." (PMID 40144515, 2025). "Alcohol is a known agonist for TRPV1 channels, yet our findings demonstrate that chronic alcohol consumption is associated with reduced thermal allodynia in oral cancer patients." (PMID 37111275, 2023). "We analyzed TRPV1 protein expression in the xenograft and 4NQO-induced oral cancer models, as well as the associated controls (sham or Matrigel only and propylene glycol, respectively)." (PMID 35260737, 2022). "For example, in an oral cancer pain model generated by inoculating squamous cell carcinoma into the gingiva of a rat, TRPV1 is overexpressed in the associated trigeminal ganglion (TG); mechanical allodynia and thermal hyperalgesia are observed in this model." (PMID 35260737, 2022). "A major class of trigeminal nociceptors express transient receptor potential (TRP) ion channels, including TRP vanilloid 1 (TRPV1), which has been implicated in oral cancer pain." (PMID 26007300, 2015). "Additionally, TRPV1 is implicated in cancer-induced pain and chemo-sensitivity, with upregulation observed in sensory neurons innervating oral cancers." (PMID 39407657, 2024). "Furthermore, alcohol consumption and tobacco use were strongly associated with the occurrence of oral cancer and were found to have a remarkable influence on TRPV1–4 receptor expression in normal oral mucosa." (PMID 28081185, 2017). "Patients with oral cancer have much higher levels of salivary linoleic acid and arachidonic acid, which activate TRPV1 and/or TRPA1 on sensory neurons and contribute to oral cancer pain." (PMID 40661938, 2025). "TRPV1 is upregulated in sensory neurons innervating oral cancers, contributing to pain and potentially affecting the tumor microenvironment." (PMID 39407657, 2024). "An anatomic basis of chemosensitivity is shown in increased expression of TRPV1 in anatomically relevant trigeminal ganglion (TG) neurons in both the xenograft and a carcinogen (4-nitroquinoline 1-oxide)-induced oral cancer mouse models." (PMID 35260737, 2022). "Lastly, we sought to determine if PAR2 mediates the TRPV1-evoked nociception secondary to oral cancer." (PMID 35260737, 2022). "Lastly, we used female mice only for the behavioral experiments to determine if TRPV1-induced aversion behavior in the presence of oral cancer is mediated by PAR2." (PMID 35260737, 2022). "Back labeled, anatomically relevant oral nociceptors respond to oral cancer by overexpressing TRPV1." (PMID 35260737, 2022). "We used PAR2 knockout mice and conditioned place aversion (CPA) to assess the role of PAR2 in oral cancer-induced TRPV1 sensitization." (PMID 35260737, 2022). "Cancer-induced increases in TRPV1 and CGRP protein expression in the TG neurons have been previously reported in association of nociception in both rat and mouse oral cancer models." (PMID 36172037, 2022). "We propose that proteases cleave and activate PAR2 on primary afferent neurons in the oral cancer microenvironment, which sensitizes TRPV1 on the same neurons." (PMID 35260737, 2022). "We have previously identified a role for the sensory neuropeptide, calcitonin gene-related peptide (CGRP), and chemosensitivity receptor, transient receptor vanilloid channel 1 (TRPV1), in oral cancer pain." (PMID 36172037, 2022). "The current study therefore explored the mechanism by which TRPV1 activities are regulated in peripheral sensory neurons during oral cancer pain." (PMID 26007300, 2015). "Taken together, our data indicate that HNSCC-infiltrating nerves have a unique transcriptome and a heightened sensitivity to noxious stimuli characterized by an increased TRPV1 expression and phosphorylation consistent with TRPV1 sensitization secondary to oral cancer." (PMID 39302290, 2024).
oral cancer (continued). "Likewise, TRPV1 is upregulated in sensory neurons innervating oral cancers, contributing to pain and potentially affecting the tumor microenvironment." (PMID 39407657, 2024). "We report that oral cancer sensitizes TRPV1 through a PAR2-mediated mechanism." (PMID 35260737, 2022). "Oral cancer pain has been attributed to release from the cancer and/or cells of the cancer microenvironment of soluble mediators and extracellular vesicles carrying pain mediators with potential to sensitize TRPV1 and TRPA1 on sensory neurons." (PMID 36368973, 2022). "Both TRPV1 and TRPA1 have been implicated in oral cancer and other pain syndromes." (PMID 36368973, 2022). "A more nuanced understanding of the contribution of chemical sensitivity, and the role of specific receptors and ion channels to oral cancer pain in patients might be obtained by assessing sensitivity to both TRPV1 and TRPA1." (PMID 36368973, 2022). "However, various cancer pain models involving several species reveal that TRPV1 is upregulated on sensory neurons that innervate oral cancers." (PMID 35260737, 2022). "Oral cancer evoked an increase in TRPV1 function and magnitude of response compared to controls." (PMID 35260737, 2022). "We study expression of TRPV1 in two oral cancer mouse models." (PMID 35260737, 2022). "There are other mechanisms, in addition to PAR2, by which oral cancer could sensitize TRPV1." (PMID 35260737, 2022). "Recent reports have shown that TRPV1 may play a role in oral cancer pain." (PMID 26007300, 2015). "In preclinical cancer models, expression of TRPV1 and TRPA1 is increased in the trigeminal or dorsal root ganglia, including in oral cancer models." (PMID 36368973, 2022). "However, the mechanism by which TRPV1 is activated during oral cancer is unknown." (PMID 26007300, 2015). "In oral cancer, tumor growth is diminished in mice lacking TRPV1+ PSNs or CGRP in orthotopic oral carcinoma mouse models." (PMID 38433844, 2024). "TRPV1 sensitization, rather than activation, is consistent with oral cancer pain during routine oral function, but not with spontaneous pain." (PMID 35260737, 2022). "While the mechanism of PAR2-mediated TRPV1 sensitization on tongue afferent neurons in the setting of oral cancer is not known, the mechanisms described for other conditions and neurons provide insight." (PMID 35260737, 2022). "We show co-expression of TRPV1 and PAR2 on tongue afferents and using a conditioned place aversion assay, demonstrate that PAR2 mediates oral cancer-induced, TRPV1-evoked sensitivity in an oral cancer mouse model." (PMID 35260737, 2022). "The aim of our study was to determine whether oral cancer leads to TRPV1-mediated chemosensitivity, and whether the mechanism involves PAR2, which is unknown in the setting of oral cancer." (PMID 35260737, 2022). "An understanding of the mechanism, and the second messengers that mediate TRPV1 sensitization, following PAR2 activation might suggest a method for pharmacologic antagonism and treatment for oral cancer pain." (PMID 35260737, 2022). "Accordingly, we tested the novel hypothesis that oral squamous cell carcinomas release certain oxidized lipids that activate TRPV1 and TRPA1 on sensory neurons, contributing to the development of oral cancer pain." (PMID 26007300, 2015). "We therefore hypothesize that oral squamous cell carcinomas release certain lipids that activate TRPV1 and/or TRPA1 on sensory neurons, contributing to the development of oral cancer pain." (PMID 26007300, 2015).
colon carcinoma (12 papers, 2013 to 2025). "This study illustrates, for the first time, that ISL increased cytosol calcium concentration and induced apoptosis via TRPV1 in colon cancer cells, giving a new understanding of the underlying mechanism of its anti‐cancer ability and making it a potential regulator for TRPV1." (PMID 40013655, 2025). "In TRPV1 knockdown mice, the increased carcinogenesis indicating that TRPV1 restricts the initiation and progression of colon cancer." (PMID 40013655, 2025). "ISL co‐culture directly upregulated the expression of transient receptor potential vanilloid‐1 (TRPV1) in colon cancer cells." (PMID 40013655, 2025). "Isoliquiritigenin (ISL) increased cytosol calcium and induced apoptosis in colon cancer cells via transient receptor potential vanilloid‐1 (TRPV1)." (PMID 40013655, 2025). "Further research demonstrated that Trpv1-deficient mice exhibited hyperactivation of the STAT and NFκB signal pathways; therefore, TRPV1 was believed to exert a protective role in colon cancer." (PMID 34131404, 2021). "Animal models have demonstrated a protective role for TRPV1 in the tumorigenesis of colon cancer, indeed TRPV1- Knockout mice exhibited lower expression of anti-inflammatory neuropeptides and greater occurrence and number of CRC compared with controls." (PMID 31652951, 2019). "Therefore, TRPV1 decreased expression in epithelium of UC samples may be associated with the exacerbated colon inflammation and consequently with the loss of the protective role of TRPV1 against colon cancer." (PMID 29914124, 2018).
endothelial dysfunction (12 papers, 2013 to 2025). In vascular diseases, endothelial dysfunction is a systemic pathological state of the endothelium (the inner lining of blood vessels) and can be broadly defined as an imbalance between vasodilating and vasoconstricting substances produced by (or acting on) the endothelium. "Its dysregulation contributes to hallmark complications of T1D, including endothelial dysfunction, impaired perfusion, nephropathy, and cardiac vulnerability—thereby identifying TRPV1 as a promising therapeutic target for restoring neurovascular homeostasis." (PMID 41463571, 2025). "In the vascular and renal systems, TRPV1 contributes to hallmark T1D complications, including endothelial dysfunction, nephropathy, and impaired cardiovascular protection, while in the central nervous system it drives neuroinflammation, cognitive decline, and emotional dysregulation." (PMID 41463571, 2025). "Dysregulated TRPV1 signaling contributes to endothelial dysfunction, impaired nitric oxide availability, renal fibrosis, and compromised cardio protection—complications frequently observed in T1D." (PMID 41463571, 2025). "The authors concluded that TRPV1 channel signaling is diminished in metabolic syndrome and this disrupted pathway can contribute to the endothelial dysfunction and the development of coronary artery disease." (PMID 33716794, 2021). "An additional elegant study proposed an alternative TRPV1-mediated mechanism of protection in endothelial dysfunction." (PMID 32471282, 2020). "In summary, this study shows that the administration of capsaicin can reverse high-glucose-induced endothelial dysfunction through TRPV1 activation." (PMID 23607427, 2013). "Second, TRPV1 activation by capsaicin ameliorated high-glucose-induced endothelial dysfunction in a UCP2-dependent manner." (PMID 23607427, 2013). "Capsaicin administration decreased the production of ROS, restored high-glucose-induced endothelial dysfunction through the activation of TRPV1 and acted in a UCP2-dependent manner in vivo." (PMID 23607427, 2013). "According to reports, TRPV1 has the potential to facilitate UCP2-mediated endothelial dysfunction." (PMID 38255767, 2024). "The authors concluded that TRPV1 activation by capsaicin might attenuate hyperglycemia-induced endothelial dysfunction through a mechanism involving the PKA and UCP2-mediated antioxidant effect." (PMID 33716794, 2021). "Subsequent studies investigated whether and how TRPV1 could be targeted to mitigate endothelial dysfunction." (PMID 32471282, 2020). "It, therefore, appears that endothelial TRPV1 could represent a useful target to prevent or attenuate endothelial dysfunction across peripheral vasculature." (PMID 32471282, 2020). "Earlier evidences showed that heat-stress-induced TRPV1 activation promoted CGRP secretion, thereby attenuating endothelial dysfunction induced by LPC, in mouse mesenteric artery and HUVECs." (PMID 32471282, 2020).
injury (12 papers, 2010 to 2025). Damage inflicted on the body as the direct or indirect result of an external force, with or without disruption of structural continuity. "Based on these findings, we demonstrated that a TRPV1 peptide targeting the K710 region markedly reduced acute pain in addition to rescuing nociceptive behavior after nerve injury." (PMID 36472910, 2023). "The pathogenesis of APAP-mediated acute liver injury involves the activation of TRPV1, TRPV4, TRPC1, TRPM2, and TRPM7 channels, which trigger the influx of Ca2+ into hepatocytes and subsequent cellular damage." (PMID 37569884, 2023). "TRPA1 and TRPV1 have been reported to be protective against the LPS-induced acute lung injury model." (PMID 32759721, 2020). "TRPA1 and TRPV1 channels are known to mediate inflammatory and nerve injury pain, making them key targets for pain therapeutics." (PMID 23497345, 2013). "TRPV1 has been shown to mediate heat hypersensitivity in other pain models such as inflammation and nerve injury, and studies have shown that these models induce increased TRPV1 expression in IB4-positive sensory neurons." (PMID 23497345, 2013). "The hypothesis tested in this study was that the mechanism of impaired arterial and cardiopulmonary baroreflex control in cisplatin‐induced renal injury in rats involves TRPV1 channels." (PMID 40349310, 2025). "This study investigated whether TRPV1 channels modulate baroreflex regulation of renal sympathetic nerve activity (RSNA) in a rat model of cisplatin‐mediated renal injury." (PMID 40349310, 2025). "Increased expression of the transient receptor potential vanilloid 1 (TRPV1) channels, following nerve injury, may facilitate the entry of QX-314 into nociceptive neurons in order to achieve effective and selective pain relief." (PMID 22962595, 2012). "The main finding of the present study was that the TRPV1 antagonist CPZ restored the arterial and cardiopulmonary baroreflex control of RSNA in cisplatin‐induced renal injury in the rat." (PMID 40349310, 2025). "Previous studies have demonstrated important roles for TRPV1, TRPM8, and TRPA1 in inflammation and nerve injury induced pain." (PMID 20205720, 2010). "Accordingly, the hypothesis was tested that TRPV1 blockade would restore the arterial and cardiopulmonary baroreflex control of RSNA in cisplatin renal injury rats." (PMID 40349310, 2025).